PIK3CA (phosphatidylinositol-4,5-bisphosphate 3-kinase catalytic subunit alpha)
Diseases named in the same sentence as PIK3CA in open-access papers (continued):
Sharing a sentence is not in itself a finding about the gene and the disease.
tumor (continued). "We reasoned that the anti‐tumour effects of cisplatin could be further enhanced in combination with DHTS, because of PIK3CA down‐regulating activity of DHTS." (PMID 32860347, 2020). "In two models (with PIK3Ca mutation and FGFR4 amplification), monotherapies decreased tumor growth without inducing regression." (PMID 32087759, 2020). "Notably, the expression levels of CHEK1, PIK3CA, and PIK3CD were significantly increased in both the primary tumor tissues and xenografts." (PMID 32610557, 2020). "Finally, we focused on patient 21, with a pT3N0 intestinal histologic subtype tumor arising from the gastric antrum characterized by gains of EGFR, MYC (OMIM 190080) KRAS, MET, and PIK3CA by OncoScan (eFigure 4C in the Supplement)." (PMID 32338752, 2020). "We present a potential therapeutic strategy of adding CQ to the PI3Ki treatment in HNSCC that is not dependent on the PIK3CA status of the tumor." (PMID 32825725, 2020). "We suspect that the tumor regression phenotype is not as robust as with αKO KPC cells because Pik3ca is not completely ablated in the αKD DT10022 cell line." (PMID 31112530, 2019). "Our result showed PIK3CA expressed differently, ranging from medium to high, in UCEC patients, which suggested tumor progression could be largely influenced PIK3CA expression quantity." (PMID 31472672, 2019). "Validation with RNA-seq data of blood platelets shows that DDR achieves the superior performance in classification of six different tumor types as well as molecular target statuses (such as MET or HER2-positive, and mutant KRAS, EGFR or PIK3CA) with smaller sets of biomarkers." (PMID 31752658, 2019). "We show that cells lacking PIK3CA are viable in vitro but are cleared by tumor-infiltrating T cells when implanted in the pancreas of immunocompetent mice." (PMID 31112530, 2019). "Our result implied the potential role of PIK3CA or other components of PI3K pathway in tumor immune microenvironment and may open a new approach for clinical anti-tumor research and anti-tumor drug development." (PMID 31472672, 2019). "Additional factors considered in the adjustment model, comprising tumor colorectal subsite location, smoking history, BMI, and mutations of KRAS, NRAS, BRAF, and PIK3CA, did not meet the 10% change in coefficient criteria for confounder selection." (PMID 31367996, 2019). "We identified 13 variants that existed in cfDNA, but not in tumor DNA from comparison analysis, and three of these were located in driver genes (ARID1A, NFE2L2 and PIK3CA)." (PMID 31641155, 2019). "Distribution of tumor location (primary, metastatic, or unknown) was similar for the assessment of each biomarker (HER2 mRNA, HER3 mRNA, PIK3CA status, and PTEN) and was well balanced across the three treatment arms (data not shown)." (PMID 31146717, 2019). "Further, PIK3CA, MYC, HIF1A and other genes with frequent alterations in primary tumours are known to dysregulate cellular metabolism by increasing the rate of glycolysis while reducing the rate of aerobic respiration; a phenomenon referred to as the Warburg effect." (PMID 31754644, 2019). "A recent study examining PIK3CA-mutant breast cancers showed that heightened PI3K-mTOR signaling is a key driver of Mcl-1 overexpression in these tumor cells, and that PI3K/mTOR inhibition impaired Mcl-1 expression, increasing PIK3CA-mutant cell sensitivity to ABT-263." (PMID 31595181, 2019). "Confirmed response was observed in 5/14 of PIK3CA-mutant tumor patients, and in 0/15 patients with tumors without known PIK3CA mutations." (PMID 30782187, 2019). "Therefore, we stained sections of paraffin embedded tumor samples for their KRAS and PIK3CA expression." (PMID 30001368, 2018).
tumor (continued). "Amplification of PIK3CA and FGFR2 might contribute to acquisition of radioresistance by the tumor in the present study." (PMID 30220971, 2018). "The patients with PIK3CA mutant tumor showed higher non-effective rate than the others (71.43 vs. 44.47%." (PMID 29970892, 2018). "Notably, PIK3CA mutant cancer cell lines have elevated 2-oxoglutarate dehydrogenase (OGDH) activity, and inhibition of this enzyme leads to reduced tumor growth in vivo." (PMID 29868481, 2018). "Firstly, using siRNA, we reduced MAP3K1 expression in two PIK3CA-mutant tumor cell lines (MCF7 and T47D) and in a breast cell line (MCF10A) that had been genetically engineered to express a common PIK3CA (H1047R) mutant (hereafter referred to as MCF10A-PI3KαH1047R)." (PMID 29765551, 2018). "However, Ki67 staining was clearly decreased all three tumor types upon treatment with C-PIK3CA-esiRNA treatment as well as in the combination group which received C-KRAS/PIK3CA-esiRNA complexes." (PMID 30001368, 2018). "PIK3CA mRNA levels were higher in non-endometrioid tumours and increased from primary tumours to their corresponding metastasis, and high mRNA levels correlated with lower survival." (PMID 30544563, 2018). "Importantly, molecular alterations in driver genes such as CTNNB1, NF1, PDGFR, PIK3CA, SH3GL1 and RBM15 were found to have a subclonal distribution, thus indicating that they have been acquired during tumor evolution." (PMID 29389895, 2018). "Testing the effect of trastuzumab on patient-derived tumor xenografts revealed HER2-positive ESCC was responsive to such treatment, but not for those carrying concurrent PIK3CA mutation." (PMID 30157855, 2018). "Consistent with previous reports, PIK3CA mutation status alone did not accurately predict outcome; WHIM18 and WHIM20 showed reduced tumour growth upon application of the inhibitors, whereas WHIM16 did not." (PMID 28348404, 2017). "In a portion of such cases of multiclonal initiation, a PIK3CA or KRAS mutant cell may acquire an additional genetic hit and progress to become the predominant tumor clone." (PMID 28755461, 2017). "The use of PI3K inhibitors has resulted in tumor stabilization and shown partial responses in PIK3CA-mutant cancers, but dramatic tumor regression has not been commonly seen in clinical trials." (PMID 28036259, 2017). "Early studies on CTCs point towards the presence of PIK3CA hotspot mutations—along with the wild-type form of this gene—in MBC patients, regardless of the PIK3CA status in the primary tumor." (PMID 28858218, 2017). "Two of these patients (patients 037 and 045) had an APC variant detected in the primary tumour but not in the PM sample whilst for the third patient (patient 051) PIK3CA, AKT1 and SMAD4 mutations were detected in the primary tumour but not in the PM sample." (PMID 29029407, 2017). "Successively, we isolated patient-matched EpCAMhigh and EpCAMlow/negative CTCs and investigated the heterogeneity of their PIK3CA status in all the collected tumor cells via Sanger sequencing." (PMID 28858218, 2017). "Our results also reinforce the concept that mutant Pik3ca is not efficient at initiating tumour formation on its own, but cooperates with other tumour-promoting genetic lesions." (PMID 29170395, 2017). "Nevertheless, every preclinical model has inherent “tumor heterogeneity” issue since not all of the cells are 100% tumor cells or from the same clone of tumor (i.e. KRAS G12D tumor cell vs coexistent PIK3CA E542K tumor cell in the same tumor)." (PMID 26909603, 2016).
tumor (continued). "As a result, we found that reduced NDRG4 mRNA expression was associated with tumor progression, as well as unfavorable outcome independent of patients' clinical features and molecular variables including KRAS, BRAF and PIK3CA mutations and MSI status." (PMID 26515606, 2016). "Interestingly, of the 8 PDXs that demonstrated tumor regression, 6 (75%) were KRAS/BRAF mutant and PIK3CA wild-type, whereas the other 2 were either all wild-type, or all mutant for RAS/RAF or PI3KCA." (PMID 26439693, 2015). "Among the genes that are mutated between 5 to 20% in TCGA GBM tumor samples, we found mutations in NF1, SPTA1, TCHH and ATRX genes, although, the other genes like PIK3R1, PIK3CA, RB1, IDH1 and KEL were not mutated in any cell line." (PMID 26496030, 2015). "In particular, some CRC PDX models exhibited significant tumor regression, particularly those harboring mutations in KRAS and BRAF with no mutation in PIK3CA." (PMID 26439693, 2015). "In addition, in three cases we detected a PIK3CA mutation in plasma DNA which was not present in the corresponding metastatic tissue sample, indicating that ctDNA may further provide insight into tumor heterogeneity and thus avoid tumor sampling bias." (PMID 25575824, 2015). "The PIK3CA status assessed in circulating tumor cells and cfDNA of liquid biopsies paves the way towards novel method for the management of patients with metastatic cancer." (PMID 28031920, 2015). "In this study, PIK3CA mutation did not correlate with other clinicopathonogical features, such as clinical FIGO stage, node metastasis, tumor size, myometrial invasion, LVSI and parametrial involvement." (PMID 26358014, 2015). "The PDX tumor gained PIK3CA and another PDX tumor gained FBXW7, PIK3CA, PTEN." (PMID 25526474, 2014). "None of the PDGFRA gains/amplifications, PIK3CA mutations, ALT phenotype or ACVR1 mutations were found in tumours with PNET histology." (PMID 25047029, 2014). "Notably, in vitro studies propose that activation of the PIK3CA/mTOR pathway may be important in tumours with deficient homologous recombination, suggesting a possible role in gaining resistance to poly ADP ribose polymerase (PARP) inhibitors in BRCA1/2 deficient tumours." (PMID 23971979, 2013). "Tumor biopsies for biomarker analysis prior to treatment were not mandated and intratumor heterogeneity in PIK3CA mutation status or limitations of detection inherent to circulating DNA mutational analysis may be responsible for the lower than expected PIK3CA mutational frequency observed." (PMID 24252402, 2013). "Therefore, prior to treatment, archival tumor tissue or fresh tumor biopsies were tested for the biomarker 1 (LRRC19 > IGFBP2) and/or biomarker 2 (PIK3CA mutant) to determine eligibility for the study in CLIA-approved space." (PMID 23342270, 2012). "We conducted a univariate analysis of survival for different patient characteristics, including age, gender, race, tumor type (mucinous vs. not), Duke's stage at diagnosis, site of primary tumor, KRAS, BRAF and PIK3CA mutations." (PMID 22675430, 2012). "The tumor from one patient harbored no less than four detected mutations (KRAS p.G12S, one PIK3CA exon 9 mutation, and two PIK3CA exon 20 mutations)." (PMID 23226389, 2012).
tumor (continued). "It has not been demonstrated that TERC is upregulated in tumor samples or cell lines in which it is amplified, and the correlation between the amplification and upregulation of the PIK3CA gene is still controversial." (PMID 22412903, 2012). "As mentioned, PIK3R1 also acts as a negative modulator of PIK3CA and has been shown to have tumor suppressor activity." (PMID 21533174, 2011). "Diffuse PIK3CA protein expression was observed in the tumor fields, whereas the upper strata were negative in adjacent normal cervical epithelium." (PMID 21663621, 2011). "These considerations suggested PTEN might also be a determinant of the efficacy of EGFR TKIs in EGFR wild-type tumours and prompted us to evaluate PTEN and PIK3CA gene copy number in our gefitinib-treated patients." (PMID 22095222, 2011). "This suggested that targeting the PIK3CA effector arm alone was not sufficient to prevent tumor growth in the NRAS mutant line." (PMID 19492075, 2009). "Seven tumours carried both KRAS and PIK3CA mutations, whereas BRAF mutations did not co-occur with the others; these frequencies closely match those in published reports and were similar between the US and Greek cohorts." (PMID 19603024, 2009). "As observed in IPC298 cells, targeting BRAF, CRAF or PIK3CA individually in SK-MEL-30 cells did not effect in vivo tumor growth." (PMID 19492075, 2009). "In summary, we demonstrated a specialized upregulation of PIK3CA oncogene in non-proliferating tumor cells induced by the microenvironment through inflammation." (PMID 18335034, 2008). "We reported the spatial dissociation between tumor cell proliferation and PIK3CA upregulation, and a specialized functional role of PIK3CA in non-proliferating tumor cells in vivo." (PMID 18335034, 2008). "The corresponding chromosomal region harbors several potential proto-oncogenes, as for example, TP73L, PIK3CA, SNO and CCNL1, which may contribute to a more aggressive tumour progression." (PMID 15700036, 2005). "The genomic background of CRC, including alterations in KRAS, NRAS, PIK3CA, AKT1, BRAF, and the tumor’s MSI status, may modulate both the abundance and biological relevance of the immune regulators TIGIT and CD155, thereby affecting immune evasion and clinical outcome." (PMID 41596586, 2026). "This highlights that RVdriver can reveal facets of tumor biology (in this case, plausibly the previously reported lack of tolerance of constitutively active PIK3CA signalling) that might be missed by existing approaches." (PMID 40514689, 2025). "Congruence for RAS/BRAF/PIK3CA was usually seen between cases analysed by clinical routine and with the Oncomine/WGS platforms but differed for 31 cases (5%), the choice of another sample with lower tumour cell count, or methodological issues, are possible reasons." (PMID 40437037, 2025). "Similar results were observed in both PIK3CA‐WT and mutant human CRC cell lines with enhanced HLA‐A,B,C levels on the cell surface after knockdown of GLS or treatment with CB‐839, suggesting that GLS inhibition‐induced tumor antigen presentation is independent of PIK3CA status." (PMID 39482885, 2025). "We could not demonstrate an association between PIK3CA alterations and event-free survival in stage I-III BC, although their presence was strongly associated with smaller tumor size, lower grade, Ki67<20%, and PR protein expression." (PMID 40507317, 2025).
tumor (continued). "Therefore, the conversion of cold KPC tumor into inflamed αKO tumor upon genetic deletion of Pik3ca in KPC was not reversed by ablation of PCCB." (PMID 40067762, 2025). "TRG with higher amplification frequencies were found to have higher mRNA expression levels in cancerous tissues than in normal tissues, such as ILIRAP, PIK3CA, PPPICA, and PLCB3, suggesting that TRG may be tumor heterogeneous in normal versus cancerous cervical samples." (PMID 38784033, 2024). "PIK3CA was the only gene that showed no significant change in normal or tumor tissue." (PMID 38505269, 2024). "In this case, instead of selecting the treatment based on the most likely, but not necessarily definitive, diagnosis, given the tumor’s known PIK3CA gain-of-function effect, alpelisib was considered and ultimately found to be extremely successful even with imperfect use by the patient." (PMID 39659799, 2024). "While monoclonal antibodies and TKIs impede HER2-positive tumor proliferation by blocking the HER2 signaling pathway, mutations in PIK3CA, absence of PTEN, and alternative signaling pathways may reduce TKI efficacy." (PMID 39582543, 2024). "While we observed an enrichment of such pathway in our recurring primary tumor set, there was no significant increased frequency in PIK3CA or AKT1 mutations when compared to frequencies reported in the TCGA sample set (PIK3CA p = 0.060; AKT1 no mutations detected)." (PMID 36732562, 2023). "However, these two anti-EGFRs are only active when the tumor cells of the patient do not present mutations at the level of the RAS, PIK3CA and BRAF genes." (PMID 37176143, 2023). "Tumor DNA sequencing in MBC is currently not yet common in clinical practice and is mostly reserved for the determination of the mutational status of the BRCA1/BRCA2, PIK3CA, and, more rarely, the ESR1 and ERBB2 genes." (PMID 36980613, 2023). "Since our analysis was performed on data obtained from whole tumor samples, including the immune component rather than micro-dissected tumor specimen, our PIK3CA signal may be from the tumor cells, immune cells, or both." (PMID 37686653, 2023). "Interestingly, in some patients, PIK3CA, KIT and NFE2L2 mutations are clonal in some tumor areas but absent in other ones, thus indicating a mixed and complex intratumoral clonal status." (PMID 36661697, 2023). "pCR was not related to PIK3CA status, Ki67 index, or stromal tumor-infiltrating lymphocytes (TILs)." (PMID 37789330, 2023).